MEN1 (menin 1)
Diseases named in the same sentence as MEN1 in open-access papers (continued):
Sharing a sentence is not in itself a finding about the gene and the disease.
kidney stones (11 papers, 2016 to 2024). "PHPT in MEN1 is associated with a high risk of developing kidney stones, due mainly to the resulting hypercalciuria (a total urinary excretion of calcium in 24 h >250 mg in females or >300 mg in males)." (PMID 38892509, 2024). "Conversely, the intake of carbonated and sugary drinks, containing fructose, is directly associated with increased urinary excretion of calcium and oxalate, with a consequent increased risk of kidney stones, and this kind of beverage should be avoided by MEN1 patients." (PMID 38892509, 2024). "The clinical manifestations of MEN1-related HPT (HPT/MEN1) are rather similar to that of sporadic HPT cases, referring to bone loss and kidney stones." (PMID 30899245, 2019). "Since eating habits play an important role in the genesis of kidney stones, it is recommended to instruct MEN1 patients with dietary advice aimed at preventing/reducing major risk factors, such as those causing urine over-saturation for calcium oxalate and calcium phosphate." (PMID 38892509, 2024). "There is no consistent data on the long-term effects of hypoparathyroidism in MEN1 patients, but it is reasonable to estimate that they are at least similar to those in the general population, as cataracts, basal ganglia calcification, nephrocalcinosis, or nephrolithiasis." (PMID 30899245, 2019). "The patient had no family history of MEN1, nephrolithiasis, or fractures." (PMID 33101196, 2020). "For patients with recurrent MEN1-related PHPT who do not meet surgical indications or refuse to be operated, cinacalcet can only maintain normal ranges of serum calcium and PTH, not reduce the risks of complications like fractures and kidney stones." (PMID 37795364, 2023). "Since the milder biochemical presentation does not align with the frequent occurrence of renal calculi in MHPT patients, the complications might be attributed to a different mechanism from that in PHPT with MEN1." (PMID 27846313, 2016).
paraganglioma (11 papers, 2017 to 2025). A benign or malignant neoplasm arising from paraganglia located along the sympathetic or parasympathetic nerves. "In addition, there is one known case of paraganglioma with MEN1 mutation." (PMID 28187001, 2017). "Sporadic panNETs arose in 141 patients with panNET-associated familial syndromes in 42 individuals: 36 with MEN1, 2 with VHL, 1 each with TSC, NF1, paraganglioma, MAX mutation and MUTYH-associated polyposis." (PMID 34163434, 2021).
prostate carcinoma (11 papers, 2010 to 2026). A carcinoma that arises from epithelial cells of the prostate gland. "The critical association of MEN1 with Androgen receptor signalling pathway and its oncogenic role in prostate cancer is well documented." (PMID 37437063, 2023). "Two newly-associated genes with potential relationships to NFκB and prostate cancer were also recovered: Menin (MEN1) and acyl-CoA binding domain containing 6 (ACBD6)." (PMID 26157642, 2015). "MEN1 was linked to cancer, prostate cancer and NFκB by two main data sources." (PMID 26157642, 2015). "The result suggests that LOH of the remaining wild-type Men1 allele may be one of the mechanisms leading to menin inactivation in the prostate cancers developed in this model, although we cannot exclude that other mechanisms may also be involved." (PMID 20663219, 2010). "Among the cell lines that are dependent on both KMT2A and MEN1 (103 lines, 13.6%) are cancer cell lines of Multiple Myeloma, Lymphoma, Prostate Cancer, Ovarian‐ and Endometrial carcinoma, Lung cancer, Kidney cancer, Breast cancer and others." (PMID 39887730, 2026). "MEN1 silencing is involved in the metastasis of prostate cancer, supporting the findings of our study." (PMID 39518122, 2024). "Menin is a tumor suppressor encoded by the MEN1 gene that is over expressed in CRPC, being correlated with low overall survival in patients with prostate cancer." (PMID 37228649, 2023). "MEN1 has an enigmatic character and can function as an oncogene in cancers including leukaemia, prostate cancer, and hepatocellular carcinoma or as a tumor suppressor in endocrine tumors." (PMID 37437063, 2023). "More importantly, our analysis revealed that, of 47 heterozygous Men1 mutant mice, six developed prostate cancers (12.8%)." (PMID 20663219, 2010). "To investigate the possible link between the development of prostate cancer and Men1 disruption, we followed a cohort of aged male heterozygous Men1 mutant mice." (PMID 20663219, 2010). "We therefore analysed the expression of CDKN1B using IHC in serial sections of prostate carcinomas from Men1+/- mice." (PMID 20663219, 2010). "Our results suggest that the study of the potential link between menin and AR expression or activity in prostatic cells would be of great interest, as the latter is deregulated in the prostate cancers found in Men1 mutant mice." (PMID 20663219, 2010). "This indeed correlates with the downregulation of CDKN1B observed in prostate carcinomas developed in our Men1 mutant mice." (PMID 20663219, 2010). "Taken together, our data revealed the development of prostate carcinomas in a small proportion of aged heterozygous Men1 mutant mice." (PMID 20663219, 2010). "Six Men1+/- mice (12.8%) developed prostate cancer, including two adenocarcinomas and four in situ carcinomas, while none of the control mice developed cancerous lesions." (PMID 20663219, 2010). "The present study therefore focused on the analysis of the prostate cancers arising in Men1 mutant mice." (PMID 20663219, 2010). "Besides the direct regulation by HIF-1α and SMAD3, through some other public ChIP-Sequencing dataset, we also found that, in PCa, CDCA2 was a directly regulated by MEN1, which function as an oncogene in prostate cancer (GEO: GSE132827)." (PMID 32509575, 2020). "The IκB complex phosphorylates NFκB to activate the cellular response to inflammation, suggesting that MEN1 may represent a novel upstream regulator of the pathway in prostate cancer." (PMID 26157642, 2015). "The results of the present study suggest that the Men1 gene could be among the rare known tumour suppressors whose disruption leads to the development of prostate cancer in mice, albeit at low incidence and with a slow progression rate." (PMID 20663219, 2010).
prostate carcinoma (continued). "Quantitation of epithelial cell nuclei displaying either no AR expression or very low staining revealed a significant increase in the number of cells with altered AR expression in prostate carcinomas from Men1 mutant mice compared with normal Men1+/+ prostate glands." (PMID 20663219, 2010). "Although one prostate cancer case was previously documented in an independent heterozygous Men1 mutant mouse cohort, to our knowledge, the present study is the first systematic evaluation and characterisation of prostate cancer related to the inactivation of the Men1 gene." (PMID 20663219, 2010). "Furthermore, our data showed that the expression of the cyclin-dependent kinase inhibitor CDKN1B (p27), a Men1 target gene known to be inactivated during prostate cell tumorigenesis, was notably decreased in the prostate cancers that developed in the mutant mice." (PMID 20663219, 2010). "Menin loss in these mutant mice may indicate a close relationship between Men1 inactivation and the development of prostate cancer, suggesting that the Men1 gene may possess oncosuppressive activity and be involved in the control of cell proliferation in prostate epithelial cells." (PMID 20663219, 2010). "This cancer development pattern in aged male heterozygous Men1 mice is similar to other non SV40-TAg GEM prostate cancer models, likely reflecting the relative late and slow features of prostate cancer development in men." (PMID 20663219, 2010). "Using a multicolor fluorescence in situ hybridization approach, the copy number alterations of six genes known to be involved in aggressive prostate cancer (PTEN, MYC, MEN1, PDGFB, CTTNBP2, and TBL1XR1) was explored in a group of recurrent and in a group of nonrecurrent prostate cancer patients." (PMID 31366128, 2019). "Although no mechanism was previously proposed, heterozygous Men1 mutant mice (Men1±) carrying an inactivated Men1 allele and mixed with C57BL6/129-Sv mouse strains developed prostate cancer as compared with wild-type (Men1+/+) littermates in aged mice (18 to 26 months)." (PMID 26157642, 2015). "To determine the effect of Men1 inactivation on prostate cancer development in mice, we followed a cohort of 47 male mutant mice (Men1+/-) and 23 wild-type (Men1+/+) age-matched littermate mice from 18 to 26 months of age, based on a previous study that showed no prostate cancer in younger mice." (PMID 20663219, 2010). "No prostate carcinoma was ever found in age-matched Men1+/+ littermates (0/23)." (PMID 20663219, 2010).
tumor syndrome (11 papers, 2006 to 2024). "Some PanNETs arise due to a genetic disease called multiple endocrine neoplasia type 1 (MEN1), an autosomal dominantly inherited tumor syndrome caused by germline mutations of the tumor suppressor gene MEN1." (PMID 37679316, 2023). "Menin was originally identified as a tumor suppressor encoded by Men1 that is mutated in the human inherited tumor syndrome, multiple endocrine neoplasia type 1 (MEN1)." (PMID 17183676, 2006). "MEN1 is an inherited tumor syndrome characterized by endocrine tumors, mainly with a parathyroid, pancreatic, or anterior pituitary origin, with a wide variety of tumors known to occur in affected individuals throughout life." (PMID 38200366, 2024). "MEN1 is a rare, autosomal-dominantly inherited tumor syndrome classically defined by tumors arising from the “3 Ps”: Parathyroids, Pituitary, and the endocrine Pancreas." (PMID 36325452, 2022). "In contrast, nucleic PRMT5 interacts with Menin and indirectly suppresses HH signaling in MEN1 tumor syndromes, such as pancreatic islet tumors." (PMID 32859041, 2020). "HRQoL generic questionnaires are not developed for a complex tumor syndrome such as MEN1 and could lead researchers to underestimate or overestimate some specific traits of the disease that influence the psychophysical status of patients." (PMID 33407684, 2021).
ependymoma (10 papers, 2012 to 2025). A WHO grade II, slow growing tumor of children and young adults, usually located intraventricularly. "NF2, MEN1 syndrome, and Turcot syndrome are the best‐known genetic syndromes associated with ependymoma." (PMID 35689525, 2022). "The authors hypothesized that there might be a common genetic etiology given the association of 11q13 translocations with ependymoma and the fact that the putative MEN1 gene had been mapped to the same chromosomal locus." (PMID 36325452, 2022). "Important genetic confirmation has been provided showing that ependymoma should be considered as a neoplasm that can occur in patients with MEN1." (PMID 38510015, 2024). "The authors concluded that ependymoma is a feature of MEN1, although uncommon compared with other MEN1-related tumors." (PMID 36325452, 2022). "The authors concluded that ependymoma can arise as part of MEN1 and should be potentially screened for in patients with this syndrome." (PMID 36325452, 2022). "Although MEN1 mutation has been associated with recurrence and progression from grade II to III ependymoma, we offer the first clear evidence that MEN1 mutation is a driver of the founding clone." (PMID 29440180, 2018). "There are reports in the literature of 11q13 abnormalities in ependymomas, and there is also a report of a MEN1 patient (MEN1 is located at 11q13, like AIP) with an ependymoma." (PMID 29849625, 2018). "However, pathogenic variants in the genes related to these familial syndromes (NF2, MEN1, APC, respectively) have only been observed in a few cases of sporadic ependymomas." (PMID 35689525, 2022). "The data that ependymoma may rarely arise as a component of MEN1 remain scarce and limited to seven case reports, two of which had documented LOH involving the MEN1 locus, and generic reports of death from ependymoma in larger series of MEN1 patients." (PMID 36325452, 2022).
facial angiofibromas (10 papers, 2014 to 2024). "Facial angiofibromas is recognized as the most frequent location in MEN1, but thoracic site was also described." (PMID 36428828, 2022). "Notably, in all studies, facial angiofibromas were more prevalent in MEN1 patients compared with their control populations." (PMID 36325452, 2022). "Moreover, these dermatological manifestations can either be localized lesions (e.g., facial angiofibroma in MEN1) or can be located on a widespread area of the skin (e.g., VHL)." (PMID 34692360, 2021).
depression (9 papers, 2018 to 2025). "Clinic study found patients with loss-of-function multiple endocrine neoplasia type 1 (Men1; protein: menin) mutations had higher levels of anxiety, depression, and fatigue compared with the general population." (PMID 40108901, 2025). "Likewise, a polymorphism of gene MEN1 (which encodes menin) was found to be significantly linked to higher risk for the onset of depression." (PMID 35530179, 2022). "Our findings show that patients with MEN1 experience higher levels of anxiety and depression than controls and face a substantial financial burden that impacts their HRQOL." (PMID 40607214, 2025). "Astrocyte-specific reductions in Men1 levels enhance NF-κB activation and IL-1β production, leading to the development of depression in mice, and these effects can be rescued by an NF-κB inhibitor." (PMID 36052143, 2022). "In 2003, a Swedish study demonstrated, for the first time, the psychosocial distress following the diagnosis of MEN1 in 29 MEN1 patients, with a higher degree of depression affecting patients categorized as having a high burden of disease and treatment." (PMID 33407684, 2021). "Our results confirmed that MEN1 patients should be followed up over time regarding their psychological status, and they should be given specific assessments for anxiety and/or depression evaluation." (PMID 33407684, 2021). "The high percentage of individuals showing signs of post-traumatic stress in our MEN1 cases is a strong indication that, after the communication of the MEN1 diagnosis, these patients have to be monitored over time, to prevent the development of depression or other long-term psychological disorders." (PMID 33407684, 2021). "The authors showed that perception of HRQoL was worse, across PROMIS 29-item profile measure domains, and levels of anxiety, depression and fatigue were all higher in adults with MEN1 compared to both the general population and individuals affected by many other chronic conditions." (PMID 33407684, 2021). "A significant increase of PV expression was found in the brain of Menin‐G503D mice, Men1‐whole‐brain deletion mice, classic CUMS and LPS‐induced depression mice." (PMID 38044302, 2024).
diabetes (9 papers, 2010 to 2025). "The high risk of MEN1 patients developing diabetes has been considered to be caused by the production of diabetogenic hormones such as glucagon by the P-NET and/or surgical resection of the pancreas." (PMID 32884006, 2020). "Patients with clinically suspected MEN1 exhibit a significantly higher risk for various metabolic syndromes, including diabetes, hypertension, hyperlipidemia, cardiovascular diseases, and malignancies, with a HR for mortality 3.7-fold higher than that of controls." (PMID 40607214, 2025). "Our findings suggest that repression of menin, a protein encoded by the Men1 gene, might be a valuable means to maintain or increase the number of functional endogenous beta cells to prevent or ameliorate diabetes." (PMID 21318185, 2010). "Although beta-cell proliferation and blood insulin levels are increased a long time after Men1 is excised in beta cells, little is known as to whether Men1 excision within a short time can prevent development of hyperglycemia in diabetes mouse models and its underlying mechanisms." (PMID 21318185, 2010). "Patients with clinically suspected MEN1 had significantly higher rates of comorbidities, including diabetes, hypertension, dyslipidemia, cardiovascular disease, and osteoporotic fractures, compared to controls." (PMID 40607214, 2025). "Comorbidities, including diabetes mellitus (22.6%), hypertension (38.1%), and dyslipidemia (20.6%), were significantly more prevalent in MEN1 patients than controls." (PMID 40607214, 2025). "We and others have previously demonstrated that MEN1 inactivation or deletion leads to various human diseases, such as renal fibrosis, diabetes and lung cancers." (PMID 37395406, 2023). "The MEN1-PD studies from France and the Netherlands reported similar rates for long-term insulin-dependent diabetes mellitus (22% and 26%, respectively) and for exocrine pancreatic insufficiency (16% and 64%, respectively)." (PMID 35454834, 2022). "In the present study, we used a multiple low-dose streptozotocin- (MLD-STZ-) induced diabetes mouse model and determined the impact of Men1 excision on STZ-induced hyperglycemia." (PMID 21318185, 2010). "We then administered multiple low-dose STZ (MLD-STZ) to the control and Men1-excised mice to induce beta cell damage and diabetes four weeks after Men1 excision." (PMID 21318185, 2010). "To determine the impact of Men1 excision on the development of diabetes, we evaluated whether Men1 excision can prevent streptozotocin- (STZ-) induced hyperglycemia using a conditional Men1 knockout mouse model." (PMID 21318185, 2010).
neuroendocrine carcinoma (9 papers, 2018 to 2025). A malignant neuroendocrine neoplasm composed of cells containing secretory granules that stain positive for NSE and chromogranin. "Our MPR and MPM mouse models are the first to underscore the cooperative roles of Men1 and Pten in cancer, particularly neuroendocrine cancer." (PMID 31160716, 2020). "This case evolved into Cushing’s syndrome due to ectopic ACTH secretion syndrome (EAS) provoked by liver metastasis originating from a pancreatic neuroendocrine carcinoma (NEC), an occurrence not previously documented in MEN1 literature for pancreatic NECs." (PMID 39104820, 2024).